HIF1A (hypoxia inducible factor 1 subunit alpha)
Diseases named in the same sentence as HIF1A in open-access papers (continued):
Sharing a sentence is not in itself a finding about the gene and the disease.
tumor (continued). "HIF-1α and VEGF are major regulators of angiogenesis and are important in tumor progression." (PMID 20003271, 2009). "Genetic inhibition tests the role of tumor cell HIF-1α and TGF-β signaling in bone metastasis but fails to address contributions from the microenvironment." (PMID 19727403, 2009). "Besides this classical regulation machinery, in the present study, we additionally demonstrate that HIF-1α and VEGF is regulated by miR-20b in tumor cells." (PMID 19893619, 2009). "HIF-1α protein was expressed strongly in the epithelium around the tumor, especially in the necrosis region, but not in normal mucosa." (PMID 20003271, 2009). "It is possible that knockdown of HIF-1α decreases osteolytic lesion development without affecting the rate of tumor growth in bone." (PMID 19727403, 2009). "Here, we provide alternative mechanism that a single microRNA, miR-20b, by virtue of its differential expression in normoxic and hypoxic microenvironment, can finely tune the expressions of HIF-1α and VEGF in tumor cells, making them to adapt to different oxygen concentrations." (PMID 19893619, 2009). "To evaluate the effect of single and combined inhibition of HIF-1α and TGF-β specifically in tumor cells in vivo, we generated a series of MDA-MB-231 cell lines which stably expressed either HIF-1α shRNA alone or in combination with a dominant-negative TGF-β type II receptor (DNRII)." (PMID 19727403, 2009). "The frequency of nuclear expression of HIF-1α in stage III carcinomas was higher than in stage I tumours, but this was not statistically significant." (PMID 19014607, 2008). "Patients with invasive edge HIF-1α- and HIF-2α- expressing tumours had a poorer overall survival than those with HIF-1α-negative/focally positive and HIF-2α-negative cancers (P=0.006)." (PMID 18283323, 2008). "Indeed, we now demonstrate that ENMD-1198 effectively inhibits activation of HIF-1α in HCC, ultimately leading to a reduction of tumor growth and vascularization in vivo." (PMID 18651980, 2008). "The overall PFI of this subgroup of patients with tumours that stained strongly for HIF-1α differed significantly than that of patients with tumours that stained weakly or were negative for HIF-1α (p < 0.05)." (PMID 19014607, 2008). "However they also point to the complexity of the cellular response to hypoxia, and incite us to decipher more deeply the mechanisms governing the dialog between HIF-1α and FGF2 to find new molecular triggers of tumour angiogenesis." (PMID 18728783, 2008). "In addition, recent works have identified as MITF transcriptional targets genes such as the CDK2, the hipoxia induced factor HIF1A and the hepatocyte growth factor receptor MET, all of them presenting functions that contribute to tumor development." (PMID 18211678, 2008). "In contrast, the distribution of the number of positive tumor nuclei and the nuclear immunostaining intensity of HIF-1α was heterogeneous but without significant differences according to the metastatic status." (PMID 18983642, 2008). "Thus by increasing the pO2 in tumor tissue with normobaric and hyperbaric oxygen it is reasonable to assume that VEGF and HIF-1α would have been down-regulated." (PMID 17263869, 2007). "However, recent studies have revealed that in this setting, upregulation of HIF-1α and HIF-2α activates distinct target genes and has contrasting effects on the growth of tumours." (PMID 17387348, 2007). "Other studies have noted HIF-1α expression at the invasive edge of tumours, but have not performed survival analyses." (PMID 17179985, 2007). "FIH-1 was also expressed in the non-neoplastic tumour elements, suggesting a possible role in regulating HIF-1α activity in these cell populations." (PMID 18096060, 2007). "In HEP2 tumours, HIF-1α increased after treatment with erlotinib, did not change with temsirolimus and decreased three-fold in the combined arm." (PMID 17342092, 2007).
tumor (continued). "Although HIF-1α expression did not correlate with tumour size, tumour grade or ER and HER2 status, tumours expressing HIF-1α were twice as likely to be associated with nodal disease (P = 0.02, OR = 1.91, 95% CI = 1.09–3.33)." (PMID 18096060, 2007). "Some of the tumours studied had large solid areas of malignant cells that showed no increase in HIF-1α expression within the central region of the cell groups but a tendency for increased expression in the peripheral layers of cells." (PMID 17179985, 2007). "In our analyses tumours with invasive edge staining had a worse prognosis compared with either HIF-1α negative or focal expression." (PMID 17179985, 2007). "However, recent studies have indicated that in this setting, upregulation of the closely related HIF-α isoforms, HIF-1α and HIF-2α, have contrasting effects on tumour growth, and activate distinct sets of target genes." (PMID 17387348, 2007). "HIF-1α-positive/p21-negative tumors had a lower apoptotic index than any other tumor samples, and patients with HIF-1α-positive/p21-negative tumors also had a significantly poorer prognosis than the other patient populations." (PMID 17166265, 2006). "The frequency of high HIF-1α expression was not apparent with tumor stage or grade according to TNM system." (PMID 16412252, 2006). "This may be related to HIF-1α regulation by hypoxia-independent mechanisms and/or greater HIF-1 degradation in totally anoxic tumours." (PMID 16404365, 2006). "HIF-1α increases angiogenesis through its regulation of VEGF expression, an effect that may be hypoxia-independent in some tumours." (PMID 16333244, 2005). "In the subgroup node negative T1/T2 tumours of the oral floor low HIF-1α expression was also correlated with a poor overall survival (p < 0.01)." (PMID 16035955, 2005). "The earlier findings that under hypoxic conditions expression of BNIP3 can be induced by the transcription factor HIF-1α prompted us to evaluate the extent to which expression of BNIP3 in haematopoietic tumour cell lines could be induced by hypoxia." (PMID 15756280, 2005). "However when there is more diffuse expression of HIF-1α as in oral SCC in the present study, the small tumour cores forming the TMA will more likely be representative." (PMID 16035955, 2005). "Well-differentiated tumours had high cytoplasmic VEGF and HIF-1α expression." (PMID 15558070, 2005). "Owing to the limited amount of tumor material, we were not able to quantitate HIF1α and HIF2α protein levels in our primary samples." (PMID 16103922, 2005). "Furthermore, between primary tumours and lymph node metastases a correlation was found for ECP%, TCP%, CA9 and Hif-1α expression (ECP% r=0.51, P<0.001; TCP r=0.77, P<0.001; CA9 and Hif-1α P<0.001)." (PMID 16251878, 2005). "When tumour cells are exposed to hypoxia, hypoxia-inducible factor-1 (HIF-1), which is a transcription factor composed of HIF-1α and HIF-1β subunits, is activated and then it promotes the transcription of several genes such as glucose transporters, glycolytic enzymes, and angiogenic factors." (PMID 12085186, 2002). "The hypoxic condition permits HIF‐1α stabilization to move to the nucleus, where it pairs up with HIF‐1β to activate hypoxia response elements in genes that control glycolysis and angiogenesis alongside cellular survival, leading to metabolic reprogramming in hypoxic tumor cells." (PMID 41521160, 2026). "Moreover, we noticed that the expression of these markers remained relatively stable in MPR patients post‐treatment, but in NPR patients, there was a marked increase in HIF‐1α, GLUT1, and TGF‐β levels after treatment, indicating tumor progression and treatment resistance." (PMID 41541656, 2026).
tumor (continued). "Importantly, RSV reduces HIF-1α protein accumulation without affecting its mRNA transcription, linking its anticancer effects to the inhibition of hypoxia-driven pathways in tumor cells." (PMID 41614951, 2026). "Composed of HIF-1α and HIF-1β subunits, HIF-1α stabilizes under hypoxia by inhibiting prolyl hydroxylase activity, activating genes such as vascular endothelial growth factor (VEGF), GLUT1, and matrix metalloproteinase (MMP) that promote tumor proliferation, angiogenesis, and invasion." (PMID 41403402, 2026). "Using HIF-1α (HRE), SREBP1 (SRE), and NRF2 (ARE) transcriptional reporters, we identified HRE-high and SRE-high CRC subpopulations with enhanced clonogenicity and invasion that drove accelerated tumor growth and increased lung metastatic burden across multiple CRC models." (PMID 42237006, 2026). "Cooperation between HIF-1α-positive and -negative cells enhances heterogeneity and tumor growth." (PMID 41179304, 2025). "Additionally, CypD OE reduced expression of hallmark EMT markers at the mRNA and protein levels without impacting HIF1α mRNA expression in the primary tumor." (PMID 40701956, 2025). "The lack of HIF1A protein decreased the expression of EPOR in tumor tissue (p = 0.0246)." (PMID 40332447, 2025). "Furthermore, silibinin may modulate immunity by suppressing HIF-1α in colon cancer (CT26) and ovarian clear-cell carcinoma (HAC-2, OVISE, and RMG-1) cells, influencing the tumor immune landscape." (PMID 40490812, 2025). "Additionally, ROS-induced NF-κB, HIF-1α, and TGF-β pathways increased uPA and MMP-9 for extracellular matrix reshaping, affecting the integrity of intercellular connections in tumor cells and activating the PI3K/AKT pathway to promote tumor cell mobility." (PMID 40847302, 2025). "HIF1A had a tendency to be downregulated in tumor tissue independent of VHL alteration." (PMID 40332447, 2025). "Besides, HIF-1α inhibition showed anti-tumor effects in the control group but not in the ASH1L depletion group." (PMID 40394007, 2025). "Indeed, BHB concentration decreased in PRCC‐TFE3 KI and PRCC‐TFE3 KI/Hif2α KO kidneys, whereas it was either increased or maintained in PRCC‐TFE3 KI/Hif1α KO and PRCC‐TFE3 KI/Hif1α/Hif2α DKO kidneys, suggesting that BHB production is inversely correlated with tumor development." (PMID 39807625, 2025). "In xenograft models, HIF2α, rather than HIF1α, has been shown to drive tumor growth." (PMID 40322886, 2025). "Although the use of 2D cell culture has been vital in revealing that HIF-1α is involved in VEGF expression, VEGF regulation in the 3D models mimics in vivo cases of tumor more closely and can provide insightful information on tumor angiogenesis and be used for screening drug candidates in vitro." (PMID 41050078, 2025). "HIF-1α overexpression was evaluated in relation to clinical variables such as age and sex and pathological features including histological grade, stage, depth of invasion (DOI), tumor size, lymphovascular invasion, perineural invasion, and worst pattern of invasion." (PMID 40546546, 2025). "Our data show that PAM + ANL combination downregulates HIF1-α expression via the PI3K/Akt pathway, and this new evidence extends the understanding of ANL’s regulation of AKT-HIF1α axis to immunomodulatory effects, beyond direct inhibition of tumor cell proliferation and stemness." (PMID 41383473, 2025). "Furthermore, the transformation of liver injury to HCC in our investigation was demonstrated by increased tumor markers (AFP, AFU, CEA, TGF-β1, YAP, TAZ, and HIF-1α) and a histological analysis of the liver that showed an increase in the size and quantity of tumor nodules in the HCC group." (PMID 40439888, 2025). "However, when tumor cells are divided in tumor tissue with and without HIF1A expression, statistical significance was observed in JAK2 expression." (PMID 40332447, 2025).
tumor (continued). "In this study, we demonstrated that ONECUT3 mediates HIF-1α deacetylation through histone deacetylase 6 (HDAC6), leading to the activation of HIF-1α transcription and its downstream glycolysis-related genes, thereby enhancing the Warburg effect and promoting tumor growth in CRC." (PMID 40032849, 2025). "Quantum dot-mediated siRNA delivery in cancer cells resulted in 50–85% gene knockdown, 30–80% tumor growth inhibition, and up to 4-fold increased cytotoxicity in combination therapies, primarily through targeted gene silencing (e.g., Survivin, TERT, HIF-1α, Bcl-2) and enhanced apoptosis." (PMID 40872479, 2025). "Meanwhile, LAPTM4B knockdown inhibited tumor cell migration and invasion, possibly by downregulation of related proteins such as matrix metalloprotein 2 (MMP-2), matrix metalloprotein 9 (MMP-9), cell cycle-dependent protein kinase 12 (CDK12) and Hypoxia-inducible factor 1-alpha (HIF-1α)." (PMID 40231269, 2025). "Hypoxia enhances the expression of PD-L1 in tumor cells through the hypoxia-inducible factor 1-alpha (HIF-1α)/mTOR pathway, and activates G protein-coupled receptor (GPR81) through lactic acid, inhibiting the antigen-presenting ability of DCs and forming type I TME, namely “cold tumor” type." (PMID 41281945, 2025). "Simultaneously, ROS activate redox-sensitive survival pathways, such as NF-κB, HIF-1α, and Nrf2, through spatiotemporal dynamic fluctuations to remodel the TME to enhance the release of inflammatory cytokines, thus supporting the survival and proliferation of tumor cells." (PMID 40563367, 2025). "This could delineate the importance of HIF1α in the maintenance of brain metastasis, such that even when not hypoxic from the lack of nearby vasculature, the tumor may favor the factors normally activated by a lack of oxygen and nutrients." (PMID 40806669, 2025). "Hence, we hypothesize that dual inhibition of HIF-1α and HIF-2α may represent a more effective strategy to delay tumor progression and enhance therapeutic outcomes in CNS hemangioblastomas." (PMID 40427061, 2025). "Furthermore, the experiments were performed under hypoxic conditions (1% O2) to closely mimic the tumor microenvironment and to explore the modulation of HIF-1α/VEGF signaling, which was not evaluated in our earlier normoxic studies." (PMID 41470183, 2025). "Tumor-suppressive miRNAs converge on glycolysis by directly repressing rate-limiting nodes—HK2 (miR-125a/miR-885-5p), PFKFB3/GLUT1/c-Myc axis (miR-192-5p), and HIF-1α (miR-199a-5p/miR-3662), reducing glucose influx and lactate production and favoring mitochondrial oxidation." (PMID 41007803, 2025). "HIF-1α has been reported to upregulate KDM5C, which mediates methylation of genes related to inflammation, stem cell differentiation, and hypoxia response, suggesting KDM5C’s potential involvement in the hypoxic tumor microenvironment and as a therapeutic target." (PMID 40450300, 2025). "Furthermore, upregulated HIF1α enhances the expression of VEGF, triggering tumor angiogenesis." (PMID 40352270, 2025). "Specifically, the average tumor size was 3,256.5 mm3 in the CpG group, while it was reduced to 1,649.7 mm3 in the TOP2A group (p<0.01), 2,242.5 mm3 in the IGF-1R group, 1,703.2 mm3 in the HIF-1α group (p < 0.05), and down to 361.7 mm3 in the TNBCvax group (p<0.0001)." (PMID 40969744, 2025). "Additionally, HIF-1α recruits TET1 to demethylate the ATF3 promoter, activating ATF3 transcription, which drives alternative splicing of P4HA1 to generate the P4HA1-9a isoform that promotes collagen deposition in the ECM and increases tumor cell invasiveness." (PMID 40813760, 2025). "Similarly, FABP7 can be upregulated by HIF-1α to enhance DGAT1 activity in macrophages, which in turn delivers lipids to CD8+ T-cells and tumor cells via exosomes, resulting in CD8+ T-cell dysfunction and tumor cell proliferation." (PMID 41226585, 2025).
tumor (continued). "Similarly, in LGG, we found that a low WWOX/HIF1A ratio fosters invasive phenotypes through HIF-1α-induced VEGF signalling and overexpression of CXCR chemokine receptors (CXCR3/4/5/6), which collectively drive angiogenesis and tumour dissemination." (PMID 41007296, 2025). "Furthermore, CTHRC1 has been shown to enhance GC metastasis via the HIF-1α/CXCR4 signaling pathway; it upregulates CXCR4 expression through HIF-1α and facilitates the migration and invasion of cancer cells, promoting tumor spread to distant organs, thus playing a crucial role in metastasis." (PMID 40978044, 2025). "Transcription factors, particularly hypoxia-inducible factor 1-alpha (HIF-1α), also play a central role in metabolic reprogramming by activating genes involved in glycolysis and lactate fermentation under low oxygen conditions, contributing to tumor aggressiveness and drug resistance." (PMID 40607060, 2025). "Moreover, the HIF-1α/LOXL2 axis further promotes tumor progression and metastasis by regulating oncogenes such as CENPF and ATAD2, activating mitotic and cell growth pathways, thereby synergistically amplifying the pro-VM effect of HIF-1α." (PMID 41019994, 2025). "However, various elements within the tumor microenvironment, including hypoxia, reactive oxygen species, nitric oxide, and specific metabolites, can affect PHD2’s hydroxylase activity, inhibiting the degradation of HIF-1α." (PMID 41213902, 2025). "Additionally, focusing solely on HIF-1α without assessing other hypoxia-related markers limits a comprehensive understanding of tumor hypoxia in OSCC." (PMID 40546546, 2025). "Upregulated genes such as ACSS1 (log2fc =0.50), PFKFB2 (log2fc = 0.57), GCK (log2fc =0.59), and PGAM2 (log2fc =0.59) indicate potential metabolic adaptations that may support tumour growth, though their impact is less pronounced compared to the WWOX/HIF1A ratio." (PMID 41007296, 2025). "Under normoxia, HIF-1α is hydroxylated by prolyl hydroxylases and degraded via the Von Hippel–Lindau (VHL) protein, but under hypoxia, it stabilizes to promote the Warburg effect by enhancing glycolysis and reducing oxidative phosphorylation, supporting tumour growth and survival." (PMID 41007296, 2025). "Moreover, PRMT5 overexpression has been shown to promote angiogenesis via activation of the hypoxia-inducible factor 1-alpha (HIF-1α)/VEGF receptor (VEGFR)/protein kinase B (Akt) signaling pathway, emphasizing its role in tumor vascular remodeling and progression." (PMID 40791817, 2025). "Binding to the CD36 receptor on tumor cells, oxLDL activates the PI3K/AKT/mTOR pathway, upregulating key glycolytic enzymes (e.g., hexokinase, phosphofructokinase, pyruvate kinase) while stabilizing HIF-1α to enhance glycolysis in both tumor cells and M2-polarized TAMs." (PMID 40563359, 2025). "In addition, HIF-1α may also interact with other oncogenic pathways, such as PI3K/AKT/mTOR and RAS/MAPK, thereby amplifying tumor progression." (PMID 39781344, 2025). "HIF1α and HIF2α, through complex mechanisms, synergistically increase IGF1R expression and activate downstream signaling pathways, such as the PI3K/AKT signaling pathway, which promotes tumor cell survival and proliferation, ultimately leading to resistance to temozolomide (TMZ)." (PMID 40290443, 2025). "HIF-1α not only helps tumor cells adapt to the hypoxic environment, but also helps T cells adapt to the hypoxic environment, enhancing the killing effect of T cells on tumors, and the absence of HIF-1α impairs the cytotoxicity of T cells." (PMID 41281744, 2025).